LINC02909 (long independently transcribed non-coding RNA 2909)
Synonyms: C12orf77
Gene: Long non-coding RNA gene on chromosome 12 (24,993,424 to 25,006,403, reverse strand). Ensembl gene ENSG00000226397.
Diseases named in the same sentence as LINC02909 in open-access papers:
LINC02909 is named in the same sentence as 2 diseases in open-access papers, as found by Europe PMC text mining. Sharing a sentence is not in itself a finding about the gene and the disease.
LINC02909 shares sentences with these, for which no sentence is quoted: tumor (2 papers); breast carcinoma (1).